SATB1 (SATB homeobox 1)
Diseases named in the same sentence as SATB1 in open-access papers (continued):
Sharing a sentence is not in itself a finding about the gene and the disease.
tumor (continued). "Moreover, SATB1/HER2 co-expression was also significantly associated with higher tumor histological grade (r = 0.306, p = 0.003)." (PMID 25956130, 2015). "So far, most of research reports that SATB1 is associated with malignant neoplasms, tumor progression and carcinogenesis diseases, which further implies that SATB1 might relate to Marek’s disease." (PMID 26471251, 2015). "Expression levels of SATB1 protein were higher in poorly-differentiated as compared with well-differentiated cell lines, and both quantity and distribution patterns of SATB1 were associated with tumor differentiation and pTNM stage." (PMID 23326301, 2013). "In cancer tissue, distribution of SATB1 showed differences associated with tumor differentiation." (PMID 23326301, 2013). "Similar to SATB2, SATB1 expression was associated with microsatellite stable tumours." (PMID 22935204, 2012). "SATB1 is a nuclear protein that has been recently reported to be a 'genome organizer' which delineates specific epigenetic modifications at target gene loci, directly up-regulating metastasis-associated genes while down-regulating tumor-suppressor genes." (PMID 19642980, 2009). "However, SATB1 may influence other prognostic parameters, as previous authors have reported associations with tumor stage and tumor grading." (PMID 24932280, 2014). "Silencing SATB1 expression by small interfering RNA (siRNA) or plasmid encoding short harpin RNA (shRNA) could inhibit, the proliferation, invasion and metastasis, and induce apoptosis of various tumor cells." (PMID 24675979, 2014). "Thus SATB1 is required and essential for tumor growth/survival and metastasis, and down-regulation or loss of SATB1 expression may impair sustained tumor growth and metastasis." (PMID 23437226, 2013). "Functionally, SATB1 KO reduces suppressive capacities of human Treg cells but boosts tumor clearance via CD4 CAR T cells in a preclinical, humanized mouse model." (PMID 42286212, 2026). "Functionally, SATB1 KO reduces human Treg cell suppressive capacities but boosts tumor clearance via CD4 CAR T cells in a preclinical, humanized mouse model." (PMID 42051317, 2026). "High levels of SATB1 expression were found to correlate with poor tumor differentiation and advanced disease stages." (PMID 40071088, 2025). "In vivo studies have also demonstrated that SATB1 downregulation suppresses tumor growth in xenograft models." (PMID 40071088, 2025). "highlighted that SATB1 is strongly expressed in HCC cell lines with high metastatic potential, indicating a correlation between SATB1 expression and aggressive tumor behavior." (PMID 40071088, 2025). "In vivo, SATB1-engineered CAR-T cells exhibited superior tumor control and promoted survival, accompanied by reduced exhaustion markers in tumor-infiltrating T cells." (PMID 41372119, 2025). "DOX and SATB1 shRNA vectors can both be guided to the tumor site under magnetic field guidance, and DOX can be released in a high-temperature-triggered manner to achieve drug therapy." (PMID 40071088, 2025). "Conversely, SATB1 overexpression accelerates tumor growth and promotes metastasis to the liver and lungs." (PMID 40071088, 2025). "Mice receiving SATB1-CAR-T cells showed superior tumor regression compared to those receiving conventional CAR-T cells." (PMID 41372119, 2025). "To assess clinical relevance, we analyzed HCC patient data (GSE111389) and observed consistent SATB1 downregulation in PD-1 high (PD-1 hi) tumor-infiltrating CD8+ T cells across all six patients." (PMID 41372119, 2025). "Bioluminescence imaging on day 7 confirmed noticeably reduced tumor burden in SATB1-CAR-T-treated mice." (PMID 41372119, 2025). "In NSCLC, SATB1 is implicated in EMT and tumor progression, while its role in SCLC, though less clear, also appears to promote aggressive cancer behavior." (PMID 40071088, 2025).
tumor (continued). "In vivo studies further demonstrate that silencing SATB1 in LS174T cells injected into mice can significantly reduce tumor growth or even completely inhibit tumor formation." (PMID 40071088, 2025). "In Glypican-3 (GPC3)-targeted CAR-T cells, SATB1 was significantly downregulated in tumor-infiltrating exhausted populations." (PMID 41372119, 2025). "In NSCLC, SATB1 expression in AC is correlated with tumor hypo-differentiation, while in SCC, higher levels of SATB1 are found in well-differentiated tumors." (PMID 40071088, 2025). "Given its central role in regulating multiple genes and pathways, SATB1 represents a promising target for tumor-specific therapies." (PMID 40071088, 2025). "Flow cytometry analysis revealed nearly 2-fold higher infiltration of human CD3+ T cells in both peripheral blood and tumor tissue of SATB1-CAR-T-treated mice." (PMID 41372119, 2025). "Several chemical agents, such as baicalein, hydrophobic statins, ganodermanontriol, and nicotinamide, have been identified for their ability to modulate SATB1 expression, leading to decreased tumor cell proliferation and metastasis." (PMID 40071088, 2025). "Given the established fact that SATB1 is upregulated in tumor tissues and cell lines derived from aggressive adenocarcinomas, the increased expression of SATB1 in 3D spheroids and the reciprocal expression to SATB2 corroborates the trend." (PMID 40689929, 2025). "Although the effect of statins on SATB2 expression was less pronounced compared to SATB1, the dynamic expression patterns of both proteins were disrupted in tumor tissues and 3D spheroids." (PMID 40689929, 2025). "In the aggressive AC cell line A549, SATB1 knockdown significantly inhibits cell proliferation, migration, and invasion but promotes apoptosis, underscoring SATB1’s role in fostering a more aggressive tumor phenotype." (PMID 40071088, 2025). "• SATB1 is overexpressed and promotes the proliferation and invasion of cancer cells, and its expression level is closely related to the depth and stage of tumor invasion." (PMID 40071088, 2025). "We observed significant downregulation of SATB1 and concomitant upregulation of PD-1 in tumor-infiltrating exhausted CAR-T cells." (PMID 41372119, 2025). "SATB1 has genome organizing functions in tumor progression, and has been described as a key regulator of EMT in cancers." (PMID 39545637, 2024). "Together, these findings suggest a sequential transcriptional activation mechanism for OPN expression, driven directly by Twist1 and indirectly by Twist1-downstream SATB1 in tumor ECs." (PMID 38416830, 2024). "Here, our study identifies a mesenchymal-like subpopulation of ECs as a major source of tumor immunosuppression, interacting with tumor Mφs to drive immunosuppressive phenotypes via Twist1/SATB1-dependent expression and secretion of OPN." (PMID 38416830, 2024). "ZNF827 mediates telomere homeostasis through recruitment of DNA repair proteins, and SATB1 has genome organizing functions in stem cells and tumor progression." (PMID 39545637, 2024). "Our findings, supported by these published results, suggest that SATB1 is a potential positive regulator of pro-tumor immunity driven by EC-Mφ interaction since SATB1 is required for the expression of OPN that can induce immunosuppressive Mφ activation." (PMID 38416830, 2024). "In sum, our work suggests a multidimensional mechanism controlling tumor immunity through spatial interaction between tumor ECs and Mφs, in which a Twist1/SATB1/OPN axis serves as a regulatory node for tumor immunosuppression." (PMID 38416830, 2024). "Differential analysis revealed that only SATB1 exhibited significant differences between normal and tumor patients." (PMID 38217031, 2024). "We reveal a spatially restricted, Twist1/SATB1-mediated sequential transcriptional activation mechanism, through which tumor ECs produce osteopontin to promote immunosuppressive macrophage (Mφ) phenotypes." (PMID 38416830, 2024).
tumor (continued). "We report the identification of a distinct mesenchymal-like population of tumor ECs that form an immunosuppressive vascular niche for Mφ polarization through a Twist1/AT-rich sequence binding protein 1 (SATB1)/osteopontin (OPN)–dependent mechanism." (PMID 38416830, 2024). "The molecular mechanism underlying OPN overexpression in cancer remains largely unclear, and our study uncovers a sequential Twist1/SATB1 transcriptional activation mechanism that leads to OPN expression in tumor ECs." (PMID 38416830, 2024). "Growing evidence suggests that SATB1 reprograms chromatin structure and transcription profile to promote tumor cell proliferation and EMT, leading to cancer progression." (PMID 38416830, 2024). "Functional enrichment analysis of the 186 regulated genes showed connections to hypoxia, glycolysis, SATB1 regulation and tumor zone peripheral versus central." (PMID 38671504, 2024). "SATB1 has been shown to have an impact on chromatin structure and interacts with various transcriptional cofactors during tumor development." (PMID 37744879, 2023). "Yu et al22 also reported that USP47 and SMURF2 can mediate CC cell proliferation and tumor progression by reversibly manipulating SATB1 ubiquitination." (PMID 37158531, 2023). "SDF-1 stimulated malignant progression and gemcitabine resistance in pancreatic cancer due to paracrine induction of SATB-1 within tumor cells." (PMID 35326670, 2022). "CAFs decrease CD8+ T lymphocyte’s function and recruit T regulatory cells (Tregs) to the tumor.CAFs generate resistance to gemcitabine through the SDF-1/SATB-1 pathway." (PMID 35626089, 2022). "Fyn and specificity protein 1 (SP1) played a significant role in the reduced expression of SATB1 and tumor progression in CRC following PRNP knockdown." (PMID 36359353, 2022). "SATB1 is abnormally overexpressed in a variety of cancers and is proposed as an oncogene to promote tumor growth and invasion 6-10." (PMID 33613773, 2021). "Multiple groups have identified the attenuation of SATB1 in MF and its relationship to disease progression and Th2 polarization, supporting the tumor-suppressive function of SATB1 in CTCLs101,132,133." (PMID 33628583, 2021). "SDF-1 upregulated the expression of SATB-1 and this upregulation supported tumour progression and resistance to treatment in PC cells." (PMID 33671588, 2021). "We performed qPCR and found that SATB1 levels were distinctly upregulated in GC tumor specimens compared to normal tissues." (PMID 34604093, 2021). "For example, SATB1 represents an attractive therapeutic target as it modifies different immune cell populations under tumor's influence, including DCs and CTLs." (PMID 33761971, 2021). "We found that the DIA IHC data alone generated the most significant prognostic model of the patient overall survival (OS), represented by three independent features: PR entropy, Ki67 bimodality, and CD8+SATB1+ cell density in the tumor tissue." (PMID 32612954, 2020). "Beyond effects on tumor cells in vitro, therapy studies in xenograft mouse models were designed to test tumor-inhibitory effects of siRNA-mediated knockdown of SATB1 more rigorously in vivo." (PMID 32451408, 2020). "In our study, besides the independent prognostic value of tumoral CD8+SATB1+ cell infiltrates, we found that SATB1 was more frequently expressed in CD8+ cells in stroma than in tumor tissue (26 and 21%, p < 0.0001, respectively)." (PMID 32612954, 2020). "The chromatin organizer protein SATB1 has been shown to be upregulated in many solid tumors and, as proto-oncogene, to affect the expression of many tumor-relevant gene products including HER receptors." (PMID 33374770, 2020). "SATB1 affects the expression of a large number of oncogenic signaling molecules, and consequently, its function has been studied in several tumor entities." (PMID 33374770, 2020). "In other tumor entities, a critical role of SATB1 in regulating the expression of receptors of the HER family has been described." (PMID 33374770, 2020).
tumor (continued). "Genome organiser SATB1 can promote BC tumour growth and can lead to metastasis by reprogramming SATB1 expression." (PMID 32350677, 2020). "On the other hand, it remains to be seen if and to what extent SATB1 inhibition will achieve therapeutic efficacies in ‘real’ tumors, beyond tumor cell lines and their corresponding xenograft tumors." (PMID 32451408, 2020). "Functional studies using an HNSCC cell line with stable shRNA-mediated SATB1 knockdown further indicate that SATB1 promotes tumor growth, invasiveness and metastasis." (PMID 32451408, 2020). "In this review, we will consider the importance of SATB1′s expression in the progression of the five most common human neoplasms: cancers of the breast, lung, colorectum, prostate and stomach." (PMID 31450715, 2019). "In our recent study, we observed diverse SATB1 expression patterns depending on the histological type of NSCLC tumour." (PMID 31450715, 2019). "SATB1 is also known to reprogram transcription profiles in tumor cells to promote tumor progression and metastasis." (PMID 31830989, 2019). "In an ovarian cancer model, tumor-driven Satb1 overexpression in terminally differentiated DCs results in a tolerant, pro-inflammatory state as evidenced by the secretion of Galectin-1 and IL-6, promoting tumor growth and immune evasion." (PMID 31921140, 2019). "SATB1′s depletion was shown to significantly reduce both the weight and the size of the xenograft tumours." (PMID 31450715, 2019). "Knockdown of SATB1 enhanced the proliferation of HL-60 cells and accelerated S phase entry in vitro, and promoted the tumor growth in vivo." (PMID 31130823, 2019). "Although its prognostic significance still needs to be evaluated, SATB1 seems to support the aggressive tumour phenotype and play a role in the stimulation of the EMT process and metastasis." (PMID 31450715, 2019). "Efforts to define the prognostic significance of SATB1′s expression in CRC tumours produced unclear results." (PMID 31450715, 2019). "Tumor size was compared from day 9 to day 16 and SATB1 shRNA mice showed a larger tumor volume compared to CTR mice." (PMID 31130823, 2019). "At the end of the experiment, tumor weight was measured and showed a significant increase in SATB1 shRNA mice compared to CTR mice (P = 0.0286)." (PMID 31130823, 2019). "Special AT-rich sequence-binding protein 1(SATB1) is a chromatin-remodeling protein that has been shown to play an important role in tumor progression and metastasis." (PMID 31130823, 2019). "The injection of SATB1-depleted LS174T cells into mice dorsal flanks resulted in a significant reduction of the growth rate or even a total inhibition of the tumour growth, depending on the shRNA used." (PMID 31450715, 2019). "This was consistent with CD8+CD45RA− T cells isolated from human ovarian cancer and compared to blood T cells which exhibited lower SATB1 expression, with higher PD‐1 expression in tumor infiltrating cells than in the periphery." (PMID 30803026, 2019). "In these tumours, a high level of SATB1 was observed to negatively affect both the overall and the disease-free survival of the patients." (PMID 31450715, 2019). "Further studies are being planned to elucidate the role of the SATB1 gene in tumor growth and spread as well as to understand how TRF is able to modulate the expression of this gene." (PMID 31783698, 2019). "SATB1′s expression was visibly related to a poor degree of tumour differentiation and an advanced TNM stage." (PMID 31450715, 2019). "Tumor was formed in 4 SATB1-shRNA1 mice and 4 CTR mice at the average time of 9 ± 1 day and 10 ± 1 day, respectively." (PMID 31130823, 2019). "In hepatocellular carcinoma clinical samples, SATB1 level correlated with tumour size, a poor degree of differentiation and the presence of lymph node metastasis." (PMID 31450715, 2019). "In the majority of the cancers studied, SATB1 was revealed to be a powerful factor influencing tumour invasion and metastasis." (PMID 31450715, 2019).
tumor (continued). "Compared with control cells, SATB-1 downregulation significantly inhibited tumor cell proliferation in SW1990 and PANC-1 cells, as shown by the CCK-8 assay." (PMID 30337520, 2018). "TGF-β, an immunoregulatory cytokine commonly present in the tumor microenvironment, led to reduced Satb1 expression in T cells and concomitant increase in PD1 expression." (PMID 30420856, 2018). "The data revealed that high expression level of SATB1 was correlated with decreased tumor differentiation, distant metastasis and lymph node metastasis in CRC, indicating its important role in tumor progression and its possible use as a tumor marker." (PMID 29867574, 2018). "This allowed to study SATB1 knockdown in established tumors, thus clearly distinguishing inhibitory effects of SATB1 knockdown on tumor growth from just reducing tumor cell grafting." (PMID 28049521, 2017). "This also demonstrates that the functional relevance and molecular effects of a given target gene (in this case SATB1) need to be evaluated in the precise tumor context." (PMID 28049521, 2017). "In light of this, and considering the multiple effects of targeting SATB1, the observed tumor-inhibitory effects are very promising with regard to future therapeutic implications." (PMID 28049521, 2017). "The global chromatin organizer SATB1 (special AT-rich sequence binding protein 1) is aberrantly expressed in multiple human neoplasms." (PMID 28636989, 2017). "The downregulation of HER1 (EGFR) upon SATB1 knockdown is in line with previous studies in other tumor entities." (PMID 28049521, 2017). "In line with the observed cell cycle deceleration, cell cycle proteins Cyclin B1 and D1 that are often overexpressed in tumor cells were downregulated upon SATB1 knockdown." (PMID 28049521, 2017). "The putative therapeutic relevance of SATB1 inhibition is further supported in an in vivo tumor xenograft mouse model, where the treatment with polymeric nanoparticles containing SATB1-specific siRNAs exerts antitumor effects." (PMID 28049521, 2017). "In contrast, another study found an inverse correlation between SATB1 expression and tumor grade/patient survival, and identified only phospho-SATB1 as relevant." (PMID 28049521, 2017). "SATB1 is reportedly overexpressed in GIN, and SATB1 overexpression significantly correlates with tumor invasion and metastasis, as determined by TNM classification." (PMID 28636989, 2017). "Summarily, our study shows that lncSHRG is able to promote cell proliferation and tumor propagation through SATB1/HES6 signaling in HCC." (PMID 29050307, 2017). "Recent studies have also shown that SATB1 is involved in tumor development, progression and metastasis." (PMID 28430598, 2017). "The function of SATB1 is also tumor-specific, and multiple effects were observed in different cancer types." (PMID 28636989, 2017). "The consequence of siRNA-mediated SATB1 knockdown was finally tested in a more relevant in vivo situation by exploring tumor-inhibitory effects in an s.c. xenograft model." (PMID 28049521, 2017). "Subsequent cellular analyses also revealed that this tumor cell inhibition upon SATB1 knockdown is based on the induction of apoptosis but also on cell cycle deceleration." (PMID 28049521, 2017). "Conversely, Satb1, a key factor of chromatin remodeling and Anp32a, a tumor suppressor and inhibitor of histone acetyl-transferases, were repressed at the transcript level." (PMID 27602772, 2016). "We showed that c-Myc expression was critical for SATB1/2-mediated tumor progression or tumor suppression." (PMID 26701851, 2016).